BTK (Bruton tyrosine kinase)
Diseases named in the same sentence as BTK in open-access papers (continued):
Sharing a sentence is not in itself a finding about the gene and the disease.
Myocardial fibrosis (1 paper, 2023). "Loss of the expression or pharmacological inhibition of BTK alleviates the process of myocardial fibrosis and cardiac dysfunction under various pathological conditions, suggesting the relationship between the amount of BTK and myocardial fibrosis." (PMID 37630287, 2023). "However, the role of phosphorylated BTK in myocardial fibrosis deserves to be explored." (PMID 37630287, 2023). "So far, little is known about the role of BTK in non-immune cells and the relationship between BTK and β-AR-induced myocardial fibrosis." (PMID 37630287, 2023).
myocarditis (1 paper, 2025). Myocarditis is a condition that is characterized by inflammation of the heart muscle (myocardium). "Kinase inhibitors, such as the Janus kinase and Bruton tyrosine kinase inhibitors, have shown promising therapeutic effects in other irAEs, such as immune-associated enteritis and myocarditis, and have demonstrated synergistic antitumor effects with ICIs." (PMID 40228248, 2025).
nasopharyngeal carcinoma (1 paper, 2022). A carcinoma arising from the nasopharyngeal epithelium. "We examined the expression of BTK, CD72, PTPN6, and VAV1 in NPC cell lines by qRT-PCR, and the expression levels of BTK, CD72, PTPN6, and VAV11 were lower in human nasopharyngeal carcinoma SUNE-1 cells compared with human nasopharyngeal epithelial cells NP69 (P<0.05)." (PMID 35957889, 2022).
oesophageal cancer (1 paper, 2022). "In addition, c-MYC amplified oesophageal cancer cell lines were observed to be synthetically lethal with silencing of BTK." (PMID 35448150, 2022). "Furthermore, BTK-inhibition with ibrutinib, an irreversible selective inhibitor of BTK, has been shown to directly inhibit growth of c-MYC and/or HER-2 amplified oesophageal cancer cell lines with downregulation of c-MYC and p-ERK, as well as corresponding cell-cycle arrest." (PMID 35448150, 2022).
oral cancer (1 paper, 2023). "It would be interesting to know which BTK isoform is expressed in these types of oral cancer." (PMID 36612306, 2023).
osteopetrosis (1 paper, 2023). Osteopetrosis, also known as marble bone disease, is a descriptive term that refers to a group of rare, heritable disorders of the skeleton characterized by increased bone density on radiographs. "Mice deficient in BTK signaling exhibited an osteopetrosis-like phenotype due to impaired bone resorption from deficient RANKL:BTK signaling in osteoclasts." (PMID 37443778, 2023).
pancreatitis (1 paper, 2023). Inflammation of the pancreas. "Importantly, targeting B cells with αCD20 monoclonal antibodies or Bruton tyrosine kinase (BTK) inhibitors offers a potential therapeutic approach for the treatment of pancreatitis." (PMID 36969002, 2023).
panniculitis (1 paper, 2025). Inflammation of the subcutaneous adipose tissue. "Previously reported dermatologic toxicities of BTK inhibitors include bruising, rash, panniculitis, and skin infections, which have all been proposed to be related to off-target inhibition of the epidermal growth factor receptor." (PMID 39897623, 2025).
pericardial effusion (1 paper, 2024). Fluid collection within the pericardial sac, usually due to inflammation. "The suggested mechanism for BTK to increase the risk of pericardial effusions is inhibition of platelet-derived growth factor receptor β (PDGFR-β) and Src family tyrosine kinases, which regulate endothelial permeability and interstitial tissue pressure." (PMID 39015770, 2024).
periodontitis (1 paper, 2023). An acute or chronic inflammatory process that affects the tissues that surround and support the teeth. "In periodontitis, BTK can aggravate periodontal bone destruction by promoting osteoclast differentiation." (PMID 37369700, 2023). "BTK inhibitors are expected to be potential drugs for treating periodontitis." (PMID 37369700, 2023).
peritonitis (1 paper, 2022). Inflammation of the peritoneum (tissue that lines the abdominal wall and covers most of the organs in the abdomen). "Using the zymosan‐induced peritonitis model of sterile inflammation, we demonstrated that acute inhibition of BTK prior to zymosan challenge reduced phosphorylation of BTK in circulating neutrophils and monocytes." (PMID 34897650, 2022). "We explored the role of BTK on migration of myeloid cells (neutrophils, monocytes and macrophages), in vitro using chemotaxis assays and in vivo using zymosan‐induced peritonitis as model systems." (PMID 34897650, 2022). "However, this mode of action does not seem entirely plausible in the context of our study as the XID mice have reduced monocyte and neutrophil recruitment in the 16‐h peritonitis model; therefore, caution should be taken in selecting the appropriate BTK inhibitor for future studies." (PMID 34897650, 2022).
polyneuropathy (1 paper, 2025). A disease or disorder affecting more than one nerve. "Ibrutinib, a first-generation BTK inhibitor, has shown promise in improving anti-MAG antibody polyneuropathy." (PMID 40351903, 2025).
progeroid syndrome (1 paper, 2020). A group of rare genetic disorders which mimic physiological aging, making affected individuals appear to be older than they are. "An immediate one could be the repurposing of ibrutinib (and other BTK inhibitors currently in clinical trials) to treat progeroid syndromes." (PMID 31736210, 2020).
pulmonary edema (1 paper, 2022). Accumulation of fluid in the lung tissues causing disturbance of the gas exchange that may lead to respiratory failure. "We found that ibrutinib effectively suppressed poly I:C- and LPS-induced pulmonary edema, pro-inflammatory cytokine release, histopathological changes, neutrophil aggregation, lymphocyte aggregation, and activation of the BTK-, FLT3-, and EGFR-related signaling pathways." (PMID 36362264, 2022).
rash (1 paper, 2025). "Meta-analysis from 4 publications (n = 574 patients) showed higher overall incidence of rash in adult ITP patients who received SYK and/or BTK inhibitors when compared to those who received placebo (RR 2.39; 95%CI: 1.01 – 5.70, p=0.05, I2 = 0%, random-effect model)." (PMID 41458387, 2025).
Respiratory distress (1 paper, 2024). Respiratory distress is objectively observable as the physical or emotional consequences from the experience of dyspnea. "We assessed the next-generation BTK inhibitor zanubrutinib in SARS-CoV-2–infected patients with respiratory distress." (PMID 39906744, 2024).
rhabdomyolysis (1 paper, 2021). Necrosis or disintegration of skeletal muscle often followed by myoglobinuria. "Its expression was similar at baseline, after UUO and rhabdomyolysis, and in control and BTK-treated mice." (PMID 34099830, 2021).
Right ventricular hypertrophy (1 paper, 2024). In this case the right ventricle is more muscular than normal, causing a characteristic boot-shaped (coeur-en-sabot) appearance as seen on anterior- posterior chest x-rays. "The Bruton tyrosine kinase (BTK) inhibitor has shown promising results in improving hemodynamics, reducing right ventricular hypertrophy, and mitigating pulmonary arterial remodeling and fibrosis, as well as reversing endothelial-to-mesenchymal transition in PAH rats." (PMID 39355239, 2024).
Schnitzler syndrome (1 paper, 2022). A rare, underdiagnosed disorder in adults characterized by recurrent febrile rash, bone and/or joint pain, enlarged lymph nodes, fatigue, a monoclonal IgM component, leukocytosis and systemic inflammatory response. "This case highlights the potential therapeutic role of Bruton tyrosine kinase inhibitors in Schnitzler syndrome." (PMID 35514998, 2022). "She fulfilled the diagnosis of Schnitzler syndrome and was treated with the Bruton tyrosine kinase inhibitor ibrutinib in combination with prednisone." (PMID 35514998, 2022).
sickle cell anemia (1 paper, 2025). "Notably, NLRP3 cooperates with Bruton's tyrosine kinase (BTK) to amplify platelet aggregation and thrombosis, particularly in diseases like sickle cell anemia (SCD), where HMGB1/TLR4-NLRP3/BTK crosstalk exacerbates thrombosis." (PMID 40520933, 2025).
steatosis (1 paper, 2021). Increased lipid within the cytoplasm of cells. "When compared to the gene correlation matrix in the steatosis and control samples within the training data, the IFIH1 gene is positively correlated to BTK in the steatosis samples." (PMID 34829865, 2021).
thromboses (1 paper, 2025). "In patients with chronic recurrent anti-PF4 thromboses, BTK inhibitors may be beneficial, and if caused by a paraprotein, antimyeloma therapy should be considered." (PMID 40236285, 2025). "As the patient repeatedly developed thromboses despite various dual anticoagulation and platelet aggregation therapies, the Bruton tyrosine kinase (BTK) inhibitor ibrutinib was considered as rescue therapy." (PMID 40236285, 2025).
thyroid cancer (1 paper, 2016). "BTK and HCK expressions are upregulated in invasive thyroid cancer compared to matched normal group, which is similar to Src." (PMID 27703281, 2016).
venous thromboembolism (1 paper, 2026). Occlusion of the lumen of a vein by a thrombus that has migrated from a distal site via the blood stream. "In contrast, estrogen-containing contraceptives carry a higher baseline risk for venous thromboembolism and potential CYP3A4-mediated interactions, so they are generally less appropriate in women receiving BTK or BCL-2 inhibitors or in those with additional VTE risk factors." (PMID 41546716, 2026).
tumor (293 papers, 2009 to 2026). "Patients with CLL and MM are particularly vulnerable due to multifaceted immunosuppression resulting from the underlying disease, the tumor microenvironment, and therapies such as BTK inhibitors or monoclonal antibodies." (PMID 40266134, 2025). "In mouse models of CLL, studies have demonstrated that a deficiency of BTK results in either the prevention or deferment of tumor development." (PMID 39169396, 2024). "Lymphocytosis is thought to be triggered by BTK inhibitor-mediated disruption of the tumor microenvironment, causing a redistribution of malignant cells from the tissue compartments to the circulating blood." (PMID 37185435, 2023). "In solid tumor models, the expression of BTK is associated with tumor growth, protection from apoptosis and poor prognosis of cancer patients." (PMID 36612306, 2023). "Then tumor immunosuppression caused by M2-TAMs was successfully blocked by inhibition of myeloid-cell recruitment responsible for IBR-induced BTK downregulation in TAMs, thus remarkably inhibiting tumor growth with negligible systemic toxicity." (PMID 36451865, 2022). "BTK deficiency and ibrutinib treatment abrogated or delayed tumor formation in a mice model of spontaneous CLL development." (PMID 36183125, 2022). "In CLL, the BCR signaling pathway is constitutively activated, in immunoglobulin heavy-chain variable (IGHV) mutated cases in particular, and the anti-tumor effect of BTKis firstly depends on the direct inhibition of BTK." (PMID 34276674, 2021). "BTK deficiency in vivo abrogated tumour formation, whereas overexpression of BTK increased tumour incidence and overall mortality." (PMID 33122850, 2021). "We have herein provided compelling evidence that CK1α sustains chronic active BCR-linked signaling cascades in MCL, namely the AKT, NF-κB and BTK-dependent pathways, and promotes tumor survival and proliferation." (PMID 34722279, 2021). "Analysis of the expression of the BTK splice isoforms in The Cancer Genome Atlas (TCGA) database using the Tumor Splice Variant Data Base (TSV DB) indicates that virtually all epithelial tumor samples contain BTK transcripts." (PMID 34307353, 2021). "Most of these genes, including SREBF1, CALM1, PCBP1, COTL1 and BTK, are tumor-related genes, which have been reported to be associated with tumorigenesis, progression and therapy." (PMID 32832275, 2020). "For example, myeloid-derived suppressor cells (MDSCs) express BTK and are present in the stroma of many different tumors, causing immunosuppression and evasion of anti-tumor immune responses." (PMID 27489860, 2016). "Simultaneous inhibition of BTK and mTORC1/2 caused apoptosis both in vitro and in vivo and resulted in tumor regression in a xenograft model." (PMID 26654227, 2015). "The dual mTORC1/2 catalytic inhibitor AZD2014 acts highly synergistically in combination with the BTK inhibitor ibrutinib and causes apoptosis both in vitro and in vivo and resulted in tumor regression in an ABC-type DLBCL xenograft model." (PMID 26654227, 2015). "Our data indicates that Ibrutinib-BTK also accumulates in tumor-associated macrophages and lymphocytes." (PMID 24759210, 2014). "In vivo, the imaging agent rapidly distributed to BTK expressing tumor cells, but also to BTK-positive tumor-associated host cells." (PMID 24759210, 2014). "Simultaneous inhibition of BTK and mTOR causes apoptosis both in vitro and in vivo and results in tumor regression in a xenograft model." (PMID 24970801, 2014).
tumor (continued). "However, resistance mechanisms wherein tumor cells bypass BTK inhibition through acquired BTK mutations, and/or activation of alternative survival mechanisms have rendered ibrutinib ineffective, imposing the need for novel therapeutics." (PMID 38687198, 2024). "The discovery of this functional interaction provided a molecular explanation as to why BTK inhibition is exquisitely toxic to tumours carrying concurrent MYD88 and CD79B mutations, which are only observed in MCD-DLBCL, while MYD88L265P-only mutant DLBCLs are insensitive to this treatment." (PMID 36289712, 2022). "Unexpectedly, the expression profile data showed that the expression of mRNA and protein of BTK was inhibited in LUAD tumor tissue, and the down-regulation of BTK was associated with poor survival, which seemed to contradict the strategy of BTK targeted therapy." (PMID 34805160, 2021). "Therefore, further investigation should be conducted to clarify the accuracy of a combined analysis of BTK expression, the amounts of tumor-infltrating B-cell isoforms, and the types of mutation-driven prior to BTK inhibitor treatment for LUAD patients." (PMID 32351880, 2020). "Therefore, Th2 responses can be induced by an interdependent network of tumor cells, CAFs and DCs, by B cells and FcRγ-expressing TAMs activated via BTK and PI3Kγ, as well as by microbiota and associated TLR-signaling." (PMID 33022971, 2020). "As venetoclax is increasingly used in combination, many regimens are designed with a lead-in using anti-CD20 monoclonal antibodies or Bruton tyrosine kinase inhibitors (BTKis) which may reduce tumor bulk, reclassify the patient’s TLS risk and facilitate less intensive monitoring procedures." (PMID 35659041, 2022). "It exerts anti-tumor effects by inhibiting BTK and downstream signaling pathways and has been a 1st-line treatment for CLL." (PMID 41559979, 2026). "BTK is present in more than just B‐cells, and ongoing work is elucidating the consequences of these ‘on‐target off‐tumour’ effects." (PMID 41447345, 2025). "Elevated BTK expression in these TSs, which matches the high BTK expression of their corresponding tumor tissues, confirmed that they accurately reflect the molecular and functional characteristics of GBM and are a suitable model for evaluating drug efficacy." (PMID 41145013, 2025). "Bulk RNA sequencing analysis of tissues from primary GBM patients revealed markedly increased (p < 0.001) BTK expression levels in tumor tissues (n = 99) compared to tumor-free cortex tissues (n = 42) consistent with prior studies." (PMID 41145013, 2025). "BTK has an important role in the activation of the B-cell receptor (BCR)-signaling pathway while the anti-apoptotic BCL-2 protein is overexpressed in tumor cells." (PMID 40864758, 2025). "By covalently binding to a cysteine residue within the BTK active site (IC50 = 0.5 nmol/L), ibrutinib irreversibly inhibits BTK activity, thereby suppressing malignant B-cell proliferation and migration to tumor-supportive lymphoid microenvironments." (PMID 41304862, 2025). "BTK promotes upregulation of the downstream NF-κB signaling pathway, which mediates the occurrence and development of B-cell lymphoma, enabling tumor cells to obtain the necessary microenvironment for survival." (PMID 40040699, 2025). "Bruton tyrosine kinase inhibitors (BTKi), initially developed to target B‐cell receptor signalling in tumour cells, have been reported to modulate the TME by altering the composition and functional profile of immune cells." (PMID 40268516, 2025). "Pharmacodynamic data revealed substantial reduction in BTK protein levels in peripheral blood and tumor tissue including at the lowest dose (50 mg)." (PMID 39941922, 2025).